YAP1 (Yes1 associated transcriptional regulator)
Diseases named in the same sentence as YAP1 in open-access papers (continued):
Sharing a sentence is not in itself a finding about the gene and the disease.
tumor (continued). "Integrating longitudinal tumor evolution studies with treatment response data may help clarify whether targeting YAP1-associated pathways could provide therapeutic benefits for a subset of SCLC patients." (PMID 40333678, 2025). "ANKRD17-overexpressing cells and tumor samples revealed significantly higher expression of yes-associated protein 1 (Yap1), indicative of a dysregulated HIPPO signaling pathway, and notably elevated AKT phosphorylation at Ser473, an indicator of a dysregulated PTEN signaling pathway (respectively)." (PMID 40458187, 2025). "Moreover, Yap1 deficiency in MΦs is also associated with the increased tumor cell proliferation index (Ki67) in the omental metastatic tumor zone, suggesting the loss of Yap1 contributes to the enhanced tumor growth." (PMID 39198883, 2024). "Based on previous studies showing that YAP1 activation plays an important role in DAB2-regulated prometastatic activity of tumor-associated macrophages, we investigated whether H pylori activated YAP1 via DAB2." (PMID 38481347, 2024). "In addition, overexpression of YAP1 induces the polarization of macrophages into the M2 phenotypes (tumor-associated macrophages) by regulating different genes such as iNOS, MerTK, IL-10, STAT3, CD163, CD206, Arg-1, CD86, and TNF-α in the naive macrophages." (PMID 39630608, 2024). "YES1, the most significantly upregulated gene among IO-exposed tumor cells in this cohort, may explain one specific mechanism via YAP1 (YES-associated protein), which is also associated with poor survival in treatment of treatment naïve ccRCC patients." (PMID 39639369, 2024). "Next, YAP1 overexpression was tested to see if it could reverse the tumor suppression caused by TPM2." (PMID 36823643, 2023). "As a key effector of the Hippo pathway, YAP1 is tightly associated with tumor metastasis." (PMID 37031206, 2023). "Additionally, tumor stiffness influences tumor and stromal cells through the transcriptional activators yes-associated protein 1 (YAP1) and WW domain-containing transcription regulator 1 (WWDR1) (TAZ)." (PMID 37468874, 2023). "In 2015, Hugo W. at al reported that up-regulation of gene expression of C-MET, down-regulation of gene expression of LEF1, tumor cell-intrinsic CpG site methylation and YAP1 pathway signature enrichment could be associated with acquired MAPKi resistance." (PMID 37568633, 2023). "In addition, recent studies have proposed that the Hippo/YAP1 pathway is inextricably linked to tumor angiogenesis." (PMID 38053093, 2023). "This pathway can be activated in GC by overexpression of HRC (Histidine-rich calcium binding protein), upregulation of MAGOH and MAGOHB, and overexpression of YAP1 (Yes-associated protein 1), and subsequently promotes the tumour cell proliferation, migration, and invasion." (PMID 37037864, 2023). "In addition, YAP1 has been identified as a tumor marker linked to drug sensitivity in various cancers." (PMID 37383164, 2023). "MT3 is related to chemotherapy resistance, which may be caused by its promotion of YAP1 expression and induction of tumor cell stemness." (PMID 38041044, 2023). "Our omics analysis of clinical data from cohorts of NSCLC revealed that dysregulation of EGFR/MAP2K1/MTOR/YAP1 signaling pathways are associated with disease progression, anticancer drug resistance, tumor immune infiltration, immune-invasive phenotypes and worse prognosis of the cohorts." (PMID 35655775, 2022). "For example, RB1 (retinoblastoma-associated protein) at S807, which could promote cell cycle progression in cancer cells, YAP1 at S109, which has been reported associated with tumor metastasis, was significantly overexpressed in tumor tissues." (PMID 36434634, 2022). "Additionally, we performed correlation analyses of YAP1 expression with RNA modification-related gene expression, tumor mutation burden (TMB), microsatellite instability (MSI), immune checkpoint regulator expression, and infiltration of immune cells." (PMID 36479120, 2022).
tumor (continued). "YAP1 target genes have been implicated to play a role in tumor progression." (PMID 35407556, 2022). "YAP1 can also regulate the expression of genes associated with secreted factors, which collectively maintain the neoplastic proliferation and tumorigenic stromal responses of the tumor microenvironment." (PMID 36289774, 2022). "Yes‐associated protein 1 (YAP1) is responsible for tumor growth, progression and metastasis." (PMID 34196131, 2022). "KDM3A is overexpressed in ccRCC and may promote tumor growth and metastasis by activating yes-associated protein 1 (YAP1) expression through epigenetic mechanisms, thus establishing a miR-335/KDM3A/YAP1 regulation axis." (PMID 33888871, 2022). "CNA-containing genes included oncogenes showing copy number gain such as Yap1, Braf, Foxo1, and Akt3 and tumor suppressors with copy number loss such as Rb1, which may favor tumor growth." (PMID 36376321, 2022). "In summary, these results demonstrated that circNEIL3-overexpressing GBM cells might drive macrophage infiltration into the tumour-associated microenvironment by activating YAP1 signalling." (PMID 35031058, 2022). "The combination treatment of PTC124 and chemotherapy drugs such as Cisplatin may be a good method of tumor therapy in YAP1 nonsense mutation HNSCC." (PMID 36428516, 2022). "Nevertheless, potential explanations that lie behind YAP1 loss might be related to tumor microenvironment, RB1 mutation status, and sensitivity to standard‐of‐care CHT." (PMID 35489038, 2022). "However, in vivo in SMS‐CTR tumor xenografts, YAP1 suppression was associated with a decline in HES1." (PMID 36037042, 2022). "The increased tumor formation rate in CIC-deficient HCC1359 mice was attenuated with YAP1 KD." (PMID 36198276, 2022). "CIC loss increases YAP1 expression to drive tumor progression." (PMID 36198276, 2022). "They demonstrated that FAT1 might reduce the tumor-initiating ability in NSCLCs by promoting Yes-associated protein 1 (YAP1) nuclear-cytoplasmic translocation." (PMID 35965328, 2022). "Finally, we proved that LINC00649 exerted its tumor-promoting effects in GC by regulating the miR-16-5p/YES-associated protein 1 (YAP1)/Hippo pathway." (PMID 33975517, 2021). "For both cytoplasmic and nuclear YAP1 staining, high levels were associated with advanced tumour stage, classical and quantitative Gleason grade, positive nodal stage, positive surgical margin, high KI67 labelling index, and early biochemical recurrence (p < 0.0001 each)." (PMID 32488048, 2020). "The in vivo experiments confirmed that fibroblasts with high expression of YAP1 could significantly promote tumour growth and were more likely to cause metastasis." (PMID 32066485, 2020). "Yes-associated protein 1 (YAP1)/Notch pathway was reported to be involved in tumor vasculogenesis." (PMID 33363174, 2020). "Also, both high and low27 YAP1 protein levels have been reported to be linked with unfavourable tumour phenotype." (PMID 32488048, 2020). "Further, using a random effects model to account for multiple tumours being recorded from each animal, we observe significant evidence of an additive dosage effect, specifically each YAP1 WT allele lost corresponds to a decrease in estimated tumour volume of ~0.03 mm3 (p = 0.0068)." (PMID 32404936, 2020). "Interestingly, the whole genome sequence analysis indicated that this patient did not carry any known oncogenetic driver mutations beside germline Yap1 mutation in tumor tissues." (PMID 30941903, 2019). "Interestingly, our clinical analysis demonstrated that low expression of YAP1 mRNA in tumor tissues was associated with favorable clinicopathological phenotypes and good prognosis." (PMID 29296196, 2017).
tumor (continued). "Furthermore, we found that down-regulated YAP1 (yes-associated protein 1) decreased tumor-initiating and metastatic capacity in small CRC cells but not in large CRC cells." (PMID 29296212, 2017). "Moreover, elevated nuclear YAP1 expression was significantly associated with clinical stage (P = 0.041) and tumor size (P = 0.023)." (PMID 29113304, 2017). "The overexpression of YAP1 is associated with tumor progression in cancer cell lines." (PMID 27705928, 2016). "We here provided direct evidence of YAP1 copy amplification in up to 23% of samples from multiple tumor types, providing compelling evidence that it represents a cancer associated alteration in a fraction of multiple tumor types." (PMID 24810989, 2014). "YAP1 loss by siRNA may protect BC cells from DNA damage-mediated apoptosis which then may promote the developing of tumor." (PMID 24223879, 2013). "Alternatively, in an advanced, androgen-independent setting, its tumor suppressor role may involve the suppression of pro-metastatic pathways such as the Yes-associated protein 1 (YAP1) pathway, mirroring a cell’s attempt to regulate excessive plasticity and invasiveness." (PMID 41511367, 2026). "Furthermore, a lower density of YAP1 and FAPα is associated with an increased density of tumor-infiltrating CD8a+ T lymphocytes with a cytotoxic immune signature, implying that fibroblasts may also engage in recruiting regulatory leukocytes to the TME." (PMID 35986369, 2022). "Thus, the Hippo/YAP1 association with SYK needs to be investigated to clarify how it might correlate with its tumor suppressing function." (PMID 33670716, 2021). "To determine whether CSCs involved in inflammation can also cause tumor development, we examined the expression of stem cell markers YAP1 and SOX9, and found that their expression in the cancer cells in the CC group was significantly higher than that in the normal cells of the control group." (PMID 33807620, 2021). "Because the positive correlation between nuclear expression of YAP1 protein and the expression of YAP1 mRNA suggested that YAP1 mRNA levels could be associated with tumor aggressiveness in GC, we assessed the clinical significance of YAP1 mRNA expression in GC." (PMID 29296196, 2017). "Additionally, YAP1 overexpression may be linked to tumor progression resulting in a worse prognosis, as observed in pediatric ACT." (PMID 27705928, 2016). "Here, we illustrated that ANLN restrains the Hippo pathway by reducing YAP1 phosphorylation level and enhancing YAP1 transcriptional activity, partly explaining the promoting-tumor effects of ANLN in ICC." (PMID 41513610, 2026). "This case expands the clinicopathologic and age spectrum of YAP1::TFE3-rearranged PEComa which needs to be distinguished from other overlapping neoplasms carrying the same gene fusion." (PMID 41790187, 2026). "Conversely, CSN6 antagonizes the ubiquitin ligase activity of SPOP, thereby stabilizing HMGCS1, which in turn activates YAP1 to drive tumor growth." (PMID 40521202, 2025). "Intranuclear YAP1 expression is vital role in predicting postoperative survival and tumor recurrence in patients with HCC." (PMID 40191726, 2025). "Fat1 activates the Hippo signalling pathway by promoting nuclear translocation of YAP1, which reduces the sphere‐forming ability and expression of tumour initiation markers in NSCLC cells, suggesting that Fat1 can inhibit NSCLC tumour initiation." (PMID 40665579, 2025). "SRC and YAP1 were also upregulated at the protein level in a significant portion of tumor samples in the cohort." (PMID 40959971, 2025). "Secondly, the genetic ablation of DUB3 markedly reduces the protein levels of YAP1 and its downstream targets, inhibits cell proliferation and tumor growth, and enhances chemosensitivity in HCC." (PMID 40307228, 2025).
tumor (continued). "To verify the correlation between YAP1 and cGAS-STING, we used hepatocellular-specific Yap1 gene knockout mice to establish liver in situ tumour-bearing mice using DEN/TCPOBOP induction." (PMID 40918140, 2025). "Consistently, blocking Ser41 phosphorylation, either by CDK4/6 inhibition or the reconstitution of the Ser41A mutant, promotes YAP1 degradation and suppresses YAP1‐driven tumor progression." (PMID 39968498, 2025). "YAP1 is an emerging node that connects mechanical cues, metabolism, and tumor cell stem-like phenotype within TME." (PMID 40822927, 2025). "By regulating the interaction between YAP1 and the cGAS-STING pathway, we demonstrate that inhibition of YAP1 can overcome immune suppression and enhance anti-tumor immunity, offering new therapeutic strategies for HCC treatment." (PMID 40918140, 2025). "It is well established that tissue or tumor stiffness-mediated mechanical signals are transduced by mechanosensitive machinery, including a key transcriptional coactivator, YAP1, in the Hippo pathway." (PMID 40813762, 2025). "Meanwhile, the density of YAP1-positive cells in the tumor parenchyma was positively correlated with the density of CD4-positive cells and FOXP3-positive cells (r = 0.635, P = 0.02; r = 0.573, P = 0.04)." (PMID 40051494, 2025). "Given YAP1's unequivocal tumor‐promoting function in human cancer, it has gained recognition as an appealing therapeutic target." (PMID 39968498, 2025). "The interplay between YAP1 and the epigenetic machinery can also manifest as a direct partnership to repress tumor-suppressive programs." (PMID 40977060, 2025). "YAP1 functions in both tumor suppression and promotion depending on the cellular environment, co-regulators, and stage of disease." (PMID 41226688, 2025). "More importantly, the strategy of targeting YAP1 to drive CAF phenotype switching from pro-tumor to anti-tumor offers a highly attractive new avenue for overcoming the immunosuppressive TME in PCa and improving immunotherapy response." (PMID 41154598, 2025). "Longitudinal single‐cell transcriptome analyses of SCLC tumours revealed the role of MYC‐mediated activation of Notch signalling in facilitating the transformation of ASCL1‐positive SCLC to a non‐NE YAP1‐positive state." (PMID 40847555, 2025). "This study highlights the effectiveness of the pH‐responsive biomimetic nanoparticle system CMD‐BHQ3‐PTL/DOX@RBCm in delivering PTL to tumor sites, with SOX9 and its upstream Hippo/YAP1 pathway playing a critical role in the underlying mechanism." (PMID 39523731, 2025). "Further studies revealed that YAP1 directly recruits M2 TAMs and activates tumor-initiating cells to facilitate M2 macrophage accumulation during the early stages of tumor formation." (PMID 41256331, 2025). "A methylation result—especially a low-confidence or borderline one—must be interpreted in light of the tumor’s morphology, IHC profile (e.g., IDH1 R132H, H3K27me3, SMARCB1), and molecular findings (e.g., IDH mutation, 1p/19q codeletion, ZFTA/YAP1 fusion)." (PMID 41487568, 2025). "For instance, IFN-gamma can induce the nuclear translocation and phase separation of YAP1 in cancer cells, thereby diminishing the tumor-immune response and contributing to immunotherapy resistance." (PMID 40784457, 2025). "We then divided all samples into two groups based on the median expression level of YAP1 in tumor cells: the YAP1-low group and the YAP1-high group." (PMID 40051494, 2025). "Upstream tumor suppressors, including MST1, LATS1/2, and FAT1/2/3/4, frequently undergo deletions or mutations, whereas downstream oncogenes such as YAP1, WWTR1, and TEAD1/2/3/4 are upregulated." (PMID 41256331, 2025).
tumor (continued). "The YAP1-related pathway is also involved in lipid droplet accumulation within tumor cells that can promote tumor growth." (PMID 41149496, 2025). "In DLBCL, overexpression of GPNMB promotes nuclear translocation of β-catenin by targeting YAP1, thereby enhancing the transcription of cyclin D1 and c-Myc, which in turn accelerates tumor proliferation." (PMID 41189944, 2025). "Building upon our prior discovery of the NAT10/SEPT9/HIF-1α positive feedback loop driving glycolytic addiction in GC11, this work unveils a novel NAT10/XIST/YAP1/VEGFA axis governing tumor vascular ecology." (PMID 40860183, 2025). "Taken together, these results indicate that the phosphorylation of DUB3 at T495 by CK2α is pivotal for promoting tumor progression through stabilizing YAP1." (PMID 39827153, 2025). "YAP1 expression was elevated in GBM versus non-tumor brain tissue (left) and negatively correlated with patient survival, particularly in female patients." (PMID 41510300, 2025). "Studies have shown that the Hippo pathway effector YAP1 influences the morphological plasticity and metastasis of tumor cells." (PMID 39994505, 2025). "Subsequently, we investigated the reciprocal interaction between SOX9 and YAP1 at both cellular and tumor tissue levels, employing immunoprecipitation (IP) experiments." (PMID 39523731, 2025). "YAP1/TAZ is considered the most common cotranscription factor to mediate the malignant biological behaviors of tumor, such as cell proliferation, migration, and invasion." (PMID 40977060, 2025). "DUB3 depletion dramatically reduced YAP1 expressions while concurrently upregulated cleaved‐PARP1 levels in tumor samples from mice treated with saline." (PMID 39968498, 2025). "In our study, we demonstrated that YAP1 positivity was significantly associated with axillary pathological complete response (p = 0.01), HER-2-enriched tumor subtype (p = 0.001), and high Ki-67 index (p = 0.028)." (PMID 40731926, 2025). "Immunofluorescence co‐localization experiments compared the co‐expression of SOX9 and p‐YAP1 (Ser351) in subcutaneous tumor tissues with SOX9 overexpression and SOX9‐KO and in human tissues between adjacent and cancerous tissues." (PMID 39523731, 2025). "Regarding the mechanisms by which cholesterol induces resistance, it has been reported that CSN6 overexpression in HCC stabilizes HMGCS1, thereby activating YAP1 signaling and promoting tumor progression." (PMID 41232667, 2025). "Combining YAP1 depletion with anti-PD-1 immune checkpoint blockade produced synergistic effects, further suppressing tumor growth, increasing CD8+; T-cell infiltration, and decreasing markers of T-cell exhaustion." (PMID 41228234, 2025). "In preclinical RCC models, the FAT1 protein functions as a tumor suppressor by acting as a cell-surface inhibitor of YAP1." (PMID 41465847, 2025). "Nonetheless, YAP1 expression persists in several patient-derived models from circulating SCLC tumor cells, adding to the ongoing controversy." (PMID 40500731, 2025). "Mechanistically, CDK4/6 directly binds to and phosphorylates DUB3, which leads to the deubiquitination and stabilization of YAP1, thereby promoting tumor growth and chemo-resistance of HCC." (PMID 40307228, 2025). "Nevertheless, both the population and density of YAP1-positive cells in the tumor stroma and parenchyma showed an increasing trend in the non-responder group." (PMID 40051494, 2025). "High KDELR1 expression led to reduced phosphorylation of YAP1, allowing it to remain active and drive tumour growth." (PMID 41294677, 2025). "Next, DUB3 is identified as a novel DUB of YAP1, exhibiting its previously uncharacterized tumor‐promoting activity in CRC primarily through stabilizing YAP1." (PMID 39968498, 2025). "To validate our findings on the prognostic value of tumor cell YAP1 expression level and TIME for immunotherapy in ES-SCLC patients, we retrieved public data for re-analysis." (PMID 40051494, 2025).